ZNF275 (zinc finger protein 275)
Description:
May be involved in transcriptional regulation.
Synonyms: LOC105373378
Tractability: No criterion of Open Targets' tractability assessment is met for any kind of drug.
Gene: Protein-coding gene on chromosome X (153,334,147 to 153,360,110, forward strand). Ensembl gene ENSG00000063587.
Subcellular location: Nucleus
Subcellular location (Human Protein Atlas): Nucleoli
Gene Ontology:
Molecular function: protein binding; DNA-binding transcription factor activity, RNA polymerase II-specific; RNA polymerase II cis-regulatory region sequence-specific DNA binding
Biological process: regulation of transcription by RNA polymerase II
Cellular component: nucleus; nuclear lumen
Homologues: Orthologues: zebrafish si:ch211-207i20.2 (29% identical). Paralogues in human: ZNF7 (39% identical), ZNF132 (38% identical), ZNF429 (38% identical), ZNF454 (38% identical), ZNF227 (38% identical), ZFP2 (38% identical), ZNF471 (38% identical), ZNF546 (38% identical), ZNF623 (38% identical), ZNF879 (38% identical), ZNF543 (37% identical), ZNF483 (37% identical), and 164 more.
Diseases named in the same sentence as ZNF275 in open-access papers:
ZNF275 is named in the same sentence as 7 diseases in open-access papers, as found by Europe PMC text mining. Sharing a sentence is not in itself a finding about the gene and the disease. The quoted sentences say what the papers report.
cervical cancer (2 papers, 2022 to 2023). A primary or metastatic malignant neoplasm involving the cervix. "Our results revealed that triciribine exerted a tumor-inhibition function in cervical cancer PDX models highly expressing ZNF275." (PMID 38067329, 2023). "Combining triciribine with cisplatin greatly broadens the therapeutic options for cervical cancer expressing high ZNF275, but further research is needed to confirm these results." (PMID 38067329, 2023). "Our findings illustrated that ZNF275 was highly expressed in cervical cancer tissues in contrast to surrounding normal tissues, which was consistently revealed in the GEO database." (PMID 38067329, 2023). "ZNF275 protein was highly expressed in cervical cancer specimens when compared with surrounding normal tissues." (PMID 38067329, 2023). "The present study indicated that cervical cancer tissue exhibited a higher expression of ZNF275 in contrast to the surrounding normal cervical tissue." (PMID 38067329, 2023). "The therapeutic impact of the combined therapy of the AKT inhibitor triciribine and cisplatin was evaluated on cervical cancer patient-derived xenograft (PDX) models expressing high ZNF275." (PMID 38067329, 2023). "A higher expression of ZNF275 was found in the cervical cancer cell lines SiHa and HeLa in comparison with the normal cervical epithelial cell line ECT1/E6E7." (PMID 38067329, 2023). "In this study, downregulated expression of ZNF275 showed a tumor-inhibitory impact on cervical cancer involving a weakening of the AKT/Bcl-2 signaling pathway." (PMID 38067329, 2023). "The application of Western blotting and immunohistochemistry (IHC) aims to assess ZNF275 protein expression and identify the signaling pathway relevant to ZNF275-mediated effects on cervical cancer." (PMID 38067329, 2023). "The present research proposes that the combination treatment of triciribine and cisplatin potentially broadens the therapeutic modality for cervical cancer expressing high ZNF275." (PMID 38067329, 2023). "ZNF275 was down-regulated in SiHa and HeLa cells to evaluate its impact on the proliferative, apoptotic, migrative, and invasive abilities of cervical cancer." (PMID 38067329, 2023). "Our results documented that triciribine sensitized cisplatin chemotherapy efficacy in cervical cancer expressing high ZNF275." (PMID 38067329, 2023). "The current research illustrated that cervical cancer tissue exhibited a higher expression of ZNF275 in contrast to the surrounding normal cervical tissue." (PMID 38067329, 2023). "Collectively, the current findings demonstrated that ZNF275 serves as a sufficiently predictive indicator of the therapeutic effectiveness of the combined treatment of triciribine and cisplatin on cervical cancer." (PMID 38067329, 2023). "This study investigated ZNF275 expression and its functional effects and molecular mechanisms in cervical cancer." (PMID 38067329, 2023). "The present study revealed that AKT and p-AKT protein were highly expressed in SiHa cells and weakly expressed in Caski cells, displaying a similar expression pattern of ZNF275 protein among different cervical cancer cell lines." (PMID 38067329, 2023). "A total of 9222 overlapping mutations were found among patient original cervical cancer (F0) and F2-, F3-PDX, of which including the Zinc-Finger Protein family genes, such as ZNF275 and ZNF280A." (PMID 36076209, 2022). "In addition, the combination treatment of triciribine and cisplatin was more effective in inducing tumor regression than single agents in cervical cancer PDX models expressing high ZNF275." (PMID 38067329, 2023). "Our findings show that ZNF275 potentially acted as a sufficiently predictive biomarker of the therapeutic effectiveness of the combined administration of triciribine and cisplatin in cervical cancer." (PMID 38067329, 2023).
cervical cancer (continued). "However, knockdown of ZNF275 exerted no discernible effect on cell proliferation and apoptosis of ECT1/E6E7, suggesting that ZNF275 mainly functioned in cervical cancer cells." (PMID 38067329, 2023). "Given our consideration of the AKT signaling pathway potentially as a therapeutically relevant target for cervical cancer cells highly expressing ZNF275, we further assessed the influence of triciribine and cisplatin on the biological behaviors of cervical cancer cells." (PMID 38067329, 2023). "Our findings show that ZNF275 potentially acts as a sufficiently predictive biomarker for the therapeutic effectiveness of the combined administration of triciribine and cisplatin in cervical cancer." (PMID 38067329, 2023). "Moreover, triciribine, which targets and reduces signaling in the ZNF275-induced AKT pathway, exhibited a tumor-suppressive role and sensitized cisplatin chemotherapy efficacy in cervical cancer expressing high ZNF275." (PMID 38067329, 2023). "Moreover, the GSE63514 dataset from the GEO database displayed that ZNF275 was more expressed in cervical cancer tissues than normal cervical tissues." (PMID 38067329, 2023). "Taken together, combination treatment of triciribine and cisplatin greatly widened the therapeutic strategies for cervical cancer expressing high ZNF275, which sheds valuable new light on chemotherapy in combination with targeted molecular therapy for cervical cancer." (PMID 38067329, 2023). "Therefore, our study intended to evaluate the cervical cancer PDX models with a high ZNF275 protein expression in responsiveness to the combination therapy of triciribine and cisplatin." (PMID 38067329, 2023). "Moreover, downregulated expression of ZNF275 showed a tumor-inhibitory impact on cervical cancer involving a weakening of the AKT/Bcl-2 signaling pathway." (PMID 38067329, 2023). "Moreover, the combination treatment of triciribine and cisplatin achieved synergistic anti-tumor activities and induced cervical cancer regression, which suggested that triciribine potentially sensitized cisplatin chemotherapy efficacy in ZNF275-expressing cervical cancer PDX models." (PMID 38067329, 2023). "Moreover, whether the AKT signaling pathway exerted functions in ZNF275 downregulation-mediated influences in cervical cancer was evaluated." (PMID 38067329, 2023). "Among different cervical cancer cell lines, the AKT and p-AKT protein expression were relatively higher in SiHa cells and relatively lower in Caski cells, which showed a consistent trend with that of ZNF275 protein expression." (PMID 38067329, 2023). "Furthermore, triciribine, targeting and reducing signaling in the ZNF275-induced AKT pathway, exhibited a tumor-suppressive role and sensitized cisplatin chemotherapy efficacy in cervical cancer cells expressing high ZNF275." (PMID 38067329, 2023). "In addition, the specific roles of ZNF275 in cervical cancer as well as other cancers have not been systematically addressed yet." (PMID 38067329, 2023). "Whether ZNF275 participates in modulating the biological behaviors of cervical cancer has not been determined to our knowledge." (PMID 38067329, 2023). "Unfortunately, the present study also uncovered that ZNF275 was not highly expressed in MS751 and Caski cells, which may be due to the intrinsic cellular characteristic differences among various cervical cancer cell lines and requires further study." (PMID 38067329, 2023).
multiple myeloma (1 paper, 2023). "That study indicated that ZNF275 expression was higher in high-risk multiple myeloma patients than in low-risk multiple myeloma patients." (PMID 38067329, 2023).
ZNF275 also shares sentences with these, for which no sentence is quoted: AIDS (1 paper); COVID-19 (1); HIV-1 infection (1); Ovarian Insufficiency (1); tumor (1).